ENSG00000253047
Gene: Small nucleolar RNA gene on chromosome 1 (150,600,539 to 150,600,659, reverse strand). Ensembl gene ENSG00000253047.
Gene Ontology:
Biological process: RNA processing
Cellular component: nucleolus
Homologues: Paralogues in human: SNORA40 (70% identical), SNORA40B (69% identical), SNORA40C (66% identical).